SNORD35B (small nucleolar RNA, C/D box 35B)
Synonyms: U35B; RNU35B
Gene: Small nucleolar RNA gene on chromosome 19 (49,497,720 to 49,497,806, forward strand). Ensembl gene ENSG00000200530.
Gene Ontology:
Biological process: RNA processing
Cellular component: nucleolus
Homologues: Orthologues: chimpanzee SNORD35B (99% identical), rat Snord35b (82% identical), mouse Snord35b (80% identical), pig SNORD35B (77% identical). Paralogues in human: SNORD35A (70% identical).
Diseases named in the same sentence as SNORD35B in open-access papers:
SNORD35B is named in the same sentence as 3 diseases in open-access papers, as found by Europe PMC text mining. Sharing a sentence is not in itself a finding about the gene and the disease. The quoted sentences say what the papers report.
renal cell carcinoma (1 paper, 2024). "We also revealed a three-snoRNA signature: SNORD15A, SNORD35B, and SNORD60 were upregulated in the tissues and urinary sediment of renal cell carcinoma (RCC), serving as novel potential biomarkers for RCC diagnosis." (PMID 38311725, 2024).
infection (1 paper, 2022). The state of being infected such as from the introduction of a foreign agent such as serum, vaccine, antigenic substance or organism. "The silencing of SNORA/Ds encoded within RPS11 (SNORD35B), SNHG3 (SNORA73A, SNORA73B), and SNHG1 (SNORD22, SNORD25, SNORD26, SNORD27, SNORD28, SNORD29, SNORD30, SNORD31) inhibited infection with influenza A virus." (PMID 36430145, 2022).
SNORD35B also shares sentences with these, for which no sentence is quoted: cancer (1 paper).